PTCH1 (patched 1)
Diseases named in the same sentence as PTCH1 in open-access papers (continued):
Sharing a sentence is not in itself a finding about the gene and the disease.
skin cancer (18 papers, 2008 to 2024). "Further, we matched the emerged NBCCS fibroblast profile to those of CAF to compare the impact of cell autonomous “pre-activated state” due to PTCH1 mutations to those of skin tumor stroma." (PMID 31979112, 2020). "As a model for Ptch1-deficiency driven skin cancer, we used the ASZ001 cell line." (PMID 29869097, 2018). "However, Ptch2 deficiency does exacerbate the skin tumor phenotype in partially Ptch1 deficient mice by deregulating epidermal lineage differentiation, and it has been found that the absence of both paralogs affects skin maintenance." (PMID 29869097, 2018). "Dysregulation of SHH-associated genes Patched 1 (PTCH1) and smoothened (SMO) has been observed in skin cancer and other malignant conditions." (PMID 35505292, 2022). "Histopathologic examination of skin tumors in our Ptch1+/−/SKH-1 animals revealed interfollicular basaloid cell proliferation in patterns virtually indistinguishable from human BCCs, and trichoblastomas typical of patients with NBCCS." (PMID 26413810, 2015). "Similar results were seen with genes in the beta catenin (Ctnnb1), hedgehog (Shh and Sufu), smoothen (Smo), patched 1 (Ptch1) and related genes which are involved in a common canonical pathway with skin cancers, notably basal cell type tumors, in mice." (PMID 25474466, 2014). "In addition, PTCH1 mRNA and protein expression analysis are also significant to understand its role in skin cancer physiopathology." (PMID 38287479, 2024). "Furthermore, when compared with BCC or SCC tumors at three different tumoral stages, the expression of Gli-1, Ptch-1, K8, and K17 was elevated in RTHα skin nevi but to a lesser extent than that observed in the skin tumors." (PMID 33509032, 2021). "In addition to the exonic deletion, we found a SNP (c.3944C>T) in exon 23 of PTCH1, which was also reported in cancers of the skin, bone and vulva." (PMID 23826113, 2013). "Ptch1+/− SKH-1 mice develop skin cancer due to UVB- or ionizing radiation-induced inflammation, the characteristics of which are similar to those of typical sporadic human skin tumors." (PMID 33671768, 2021).
colorectal cancer (17 papers, 2010 to 2024). A primary or metastatic malignant neoplasm that affects the colon or rectum. "Another example is that the association of PTCH1 mutation with improved outcome of PD-1 blockade was seen in both colorectal cancer and NSCLC (the present study)." (PMID 38951894, 2024). "PTCH1 CTD mutations are present in ~2.8% of colorectal cancers, ~2.3% gastric cancer and ~5.8% of endometrial cancers." (PMID 36672319, 2023). "Germline pathogenic PTCH1 variant was also described in one colorectal cancer patient whose cancer showed microsatellite instability and wild-type MMR genes." (PMID 37628631, 2023). "The presence of PTCH1 driver mutation in a colorectal cancer suggests that autocrine activation of Hh signaling can, in some cases, promote colorectal tumorigenesis." (PMID 24368541, 2013). "Here, we report a loss-of-function mutation of PTCH1, a tumor suppressor in the Hh pathway, in a colorectal cancer that exhibits transcriptional upregulation of the downstream Hh gene GLI1." (PMID 24368541, 2013). "The sensitivity and specificity of PTCH1 for predicting metastatic risk of colorectal cancer should be evaluated further in larger samples." (PMID 20230186, 2010). "Lower levels of PTCH1 have been linked to a higher risk of metastasis in human colorectal cancer." (PMID 32857815, 2020). "In addition to the P681L mutation, three additional nonsynonymous PTCH1 mutations found in colorectal cancers occurred at codons that were also mutated in other cancers." (PMID 24368541, 2013). "Variations in the GLI1 and PTCH1 levels were consistent with those observed between the various colorectal cancer cell lines." (PMID 37048132, 2023). "Papadopaulos and co-workers reported an overexpression of Ptch1 in colorectal cancers, and their analysis of esophageal biopsy specimens from patients treated with chemotherapy revealed elevated levels of Ptch1 expression in 76% of the cases." (PMID 35631574, 2022). "The seven significant colorectal cancer associated genes shortlisted from the differentially expressed genes were CALD1, CTNNB1, CXCL14, PTCH1, CXCL8, TNFAIP3, and NNMT after mapping with PubMed, OMIM, MeSH, and PMC databases." (PMID 32523911, 2020). "To further validate this conclusion, we engineered the CTD truncation at S1223 in a colorectal cancer cell line without mutations in PTCH1 by CRISPR/Cas9." (PMID 36672319, 2023). "In addition to PTCH1, SMO and SUFU were also mutated or otherwise altered in colorectal cancers at low frequency." (PMID 24368541, 2013). "As E-cadherin has been implicated in CRC metastasis, our observation implied that PTCH1 might be involved in metastasis of colorectal cancer possibly through affecting the expression of E-cadherin." (PMID 20230186, 2010). "Our study revealed that PTCH1 expression was inversely correlated with metastasis of CRC, which suggested that it could be a potential biomarker for predicting the metastatic risk of colorectal cancer." (PMID 20230186, 2010). "Dependent receptors (e.g., deleted in colorectal cancer (DCC) and patched 1 (PTCH1)) are activated when their specific ligand levels fall below a specific threshold." (PMID 38254620, 2023). "Recent studies have also confirmed that PARK7 promotes the proliferation and metastasis of colorectal cancer by activating the Hh and Wnt signaling pathways, and that PARK7 increases proteins involved in the Hh signaling pathway, including GLI1, GLI2, and PTCH1." (PMID 39276379, 2024).
osteosarcoma (17 papers, 2010 to 2025). A usually aggressive malignant bone-forming mesenchymal neoplasm, predominantly affecting adolescents and young adults. "The several novel variants of ALK, BLM, PTCH1 in this patient might expand the mutational spectrums of the osteosarcoma." (PMID 35057767, 2022). "In addition, we find that Wnt5a/6 are up-regulated in-Ptch1 deficient MSCs and that β-Catenin is highly activated in mouse enchondroma and osteosarcoma samples." (PMID 31482846, 2019). "Our current study clearly shows that the canonical pathway plays a critical role in Ptch1 deficiency-induced enchondroma and osteosarcoma formation, as inhibitors for Smo or Gli1/2, which are developed as candidate drugs to treat cartilage and bone tumors, suppressed tumorigenesis." (PMID 31482846, 2019). "In osteosarcoma, overexpression of Hedgehog ligands and receptors, as well as mutations in pathway components, such as SMO and PTCH1, can result in increased Hedgehog signaling activity, promoting tumor growth and metastasis." (PMID 38428404, 2024). "Gene expression analyses by real-time PCR revealed overexpression of Shh, Ihh, Ptch1, Smo, and Gli2 in osteosarcoma cell lines." (PMID 37815662, 2023). "In contrast, examination of osteosarcoma biopsy specimens showed overexpression of Smo, Ptch1, and Gli compared to normal bone tissue cells." (PMID 37815662, 2023). "This study for the first time shows that deletion of Ptch1 alone in Prrx1+ MSCs results in development of enchondromas and osteosarcomas in the same mice." (PMID 31482846, 2019). "We further show that Ptch1-/-enchondromas and osteosarcomas are derived from Prrx1+ lineage located at cartilage and periosteal bone, respectively and they express limited levels of markers for differentiated chondrocytes and osteoblasts, respectively." (PMID 31482846, 2019). "The Gli-specific inhibitor GANT61 suppresses the levels of Gli1/2, Ptch1 and Pax6, cell growth and colony formation in osteosarcoma cells." (PMID 29899399, 2018). "In the current study, we determined the levels of expression of Hedgehog pathway components (IHH, SMO, PTCH1, and GLI1) in primary human osteosarcoma specimens and examined the association with clinical characteristics and patient outcome." (PMID 24799831, 2014). "Of most importance was the finding that markers of active Hhï¿1⁄2GLI signaling, GLI2 and PTCH1 were consistently up-regulated in the examined osteosarcoma cells, demonstrating the aberrant Hh-GLI pathway activation." (PMID 20067614, 2010). "Moreover, Ptch1 deletion led to development of osteoarthritis-like phenotypes, exostoses, enchondroma, and osteosarcoma in Smo-Gli1/2-dependent manners." (PMID 31482846, 2019). "However, higher expression of the Hh ligand (Ihh) and its downstream target genes PTCH1 and Gli1 was observed in 43 clinical specimens of high-grade human osteosarcoma." (PMID 29899399, 2018). "Decreased expressions of Gli1, Gli2, Ptch1, and PAX6 were observed after treatment of canine osteosarcoma cells using GANT61." (PMID 37815662, 2023). "The results showed that knockdown of CNOT1 significantly inhibited the expression of GLI1, PTCH1, and PTCH2 in osteosarcoma cells." (PMID 28188704, 2017). "In this study of 43 osteosarcoma samples, we detected high expression levels of the Hedgehog ligand gene, IHH, and IHH target genes, PTCH1 and GLI1, in most osteosarcoma samples." (PMID 24799831, 2014). "In this study of 43 high-grade human osteosarcoma samples, we detected high expression levels of the Hedgehog ligand gene, IHH, and target genes, PTCH1 and GLI1, in most samples." (PMID 24799831, 2014). "Real-time PCR revealed that ATO prevented the transcription of GLI target genes, including PTCH1, GLI1, and GLI2, in human osteosarcoma cell lines." (PMID 23861973, 2013). "Real-time PCR showed that ATO decreased the expression of Hedgehog target genes, including PTCH1, GLI1, and GLI2, in human osteosarcoma cell lines." (PMID 23861973, 2013).
osteosarcoma (continued). "In the present study, we found that Shh, Dhh, PTCH1, SMO, GLI1 and GLI2 transcripts were over-expressed in osteosarcoma cell line." (PMID 20067614, 2010). "Cyclopamine at 20 μM reduced mRNA levels of PTCH1 and GLI2 in osteosarcoma cells by more than 60%, consistent with the expected down-regulation of Hh-GLI signaling." (PMID 20067614, 2010). "However, NGS revealed a complex genome lacking the characteristic EWSR1-associated rearrangements and instead identified deletions in RB1, PTCH1, and ATRX, confirming the diagnosis of osteosarcoma." (PMID 40115314, 2025). "Variable levels of IHH, SMO, PTCH1, and GLI1 expression were observed in the osteosarcoma samples." (PMID 24799831, 2014). "In addition, SMO, PTCH1, and GLI2 were over-expressed in osteosarcoma biopsy specimens'." (PMID 20067614, 2010).
colon carcinoma (15 papers, 2010 to 2026). "Since the previous findings were obtained with immortalised normal cells, we next investigated whether frameshift-causing mutations of PTCH1 could increase the autophagic flux in colon cancer cells." (PMID 36672319, 2023). "We next engineered PTCH1 indel mutations at S1223 by CRISPR/Cas9 in SW620 colon cancer cells." (PMID 36672319, 2023). "The non-canonical hedgehog pathway was reported to increase the expression of WNT through the involvement of PTCH1 in colon carcinoma." (PMID 37700842, 2023). "PTCH1 was found to be altered in 2.76% of all cancers but was predominantly altered in colon cancer (TCGA data portal, My Cancer Genome database)." (PMID 37626695, 2023). "Proof of principle was obtained by engineering a truncation in PTCH1 in two colon cancer cells by CRISPR/Cas9." (PMID 36672319, 2023). "We recently reported mutations in exons encoding the C-terminal tail of PTCH1 in colon cancer, which result in premature truncation but do not impair canonical Hedgehog signalling." (PMID 41748949, 2026). "Altogether, these findings reveal that PTCH1 C-tail truncating mutations promote colon cancer tumourigenesis through a non-canonical GLI-PI3K positive loop." (PMID 41748949, 2026). "In this study, we show that colon cancer cells engineered by CRISPR/Cas9 to express endogenous truncated PTCH1 have enhanced proliferation, colony formation, anchorage-independent growth and form larger tumours in vivo than isogenic cells expressing wild-type PTCH1." (PMID 41748949, 2026). "To this end, we used SW620 cells, a colon cancer cell line without mutations in the Hh pathway in which we engineered an oncogenic PTCH1 mutation using CRISPR/Cas9 technology." (PMID 35159339, 2022). "Hedgehog/Gli1 signaling related components, PTCH1 and Gli1, are over-expressed in colon tumor." (PMID 25386960, 2014). "Interestingly, in human colon cancer biopsies, overexpression of the HH pathway components sonic hedgehog (SHH), patched 1 (PTCH), or GLI1, was found to be an indicator of poor prognosis." (PMID 36289675, 2022). "Thus, using qRT-PCR, the expression of GLI1, PTCH1, GLI2 and SHH was determined in all human colon carcinomas examined." (PMID 20957031, 2010).
gastric cancer (15 papers, 2013 to 2025). A primary or metastatic malignant neoplasm involving the stomach. "Following this preliminary result, further studies of molecular mechanisms involved in regulating the PTCHI methylation changes and the association between PTCH1 hypermethylation and the biological features of gastric cancer are required." (PMID 25013484, 2014). "The missing or mutated PTCH1 gene has rarely been reported in gastric cancer in previous studies." (PMID 25013484, 2014). "The detection of methylation of the PTCH1 gene may become a diagnostic marker of gastric cancer, which may provide guidance for the treatment and evaluation of gastric cancer." (PMID 24255663, 2013). "The high level of methylation of the PTCH1 gene in the gastric cancer cell line may be one of the pathogenic mechanisms of certain forms of gastric cancer." (PMID 24255663, 2013). "The high level of methylation in the CpG islands of the PTCH1 gene may be associated with the occurrence and development of gastric cancer." (PMID 24255663, 2013). "Repression of PTCH1 in a gastric cell line was shown to correlate with high level of methylation of CpG islands at regulatory sequences and this could be associated with the development of gastric cancer." (PMID 25018881, 2014). "However, the association between PTCH1 methylation and gastric cancer is rarely reported." (PMID 25013484, 2014). "While both PTCH1 and PTCH2 receptors are associated with numerous human cancers, concerning gastric cancer, especially PTCH1 is the relevant gene product." (PMID 29725500, 2018). "Treatment with 5-azacitidine (AZA) resulted in the unmethylation of PTCH-1 promoter, upregulation of PTCH1 expression, and apoptosis in gastric cancer cell lines." (PMID 28203307, 2017). "In conclusion, the hypermethylation of the PTCH1 gene promoter region in gastric cancer was observed in the present study." (PMID 25013484, 2014). "In order to further study the association between PTCH1 expression and promoter methylation, the correlation between PTCH1 gene methylation and its relative expression in gastric cancer and adjacent normal tissues was analyzed in 20 gastric cancer patients." (PMID 25013484, 2014). "PTCH1 expression was negatively correlated with promoter methylation in the gastric cancer tissues, their corresponding adjacent normal tissues and the gastric cancer AGS cell line (r=−0.591, P=0.006)." (PMID 25013484, 2014). "Taking AGS as a reference sample, the relative expression levels of PTCH1 in the gastric cancer and adjacent normal tissues were 1.26±0.89 and 2.74±1.67, respectively." (PMID 25013484, 2014). "Demethylation agent 5-Aza-dC can reverse the methylation status of PTCH1 and regulate the expression of PTCH1, indicating its potential role in gastric cancer treatment." (PMID 25013484, 2014). "High methylation levels of PTCH1 were observed in the gastric cancer tissues and the cancer cell lines." (PMID 25013484, 2014). "Few studies have also reported the correlation between the methylation of the PTCH1 gene and gastric cancer." (PMID 25013484, 2014). "More scientific experimental evidence regarding PTCH1 gene hypermethylation as a gastric cancer marker and its function in guiding the treatment and prognosis of gastric cancer are also required from these studies." (PMID 25013484, 2014). "The expression of the PTCH1 gene in the gastric cancer tissues and gastric cancer AGS cell line were observed by qPCR." (PMID 25013484, 2014). "The purpose of this investigation was to understand the role of PTCH1 gene methylation in the development of gastric cancer and to provide guidance for the clinical diagnosis and treatment of gastric cancer." (PMID 24255663, 2013). "CpG island hypermethylation of the PTCH1 gene was observed in the AGS gastric cancer cell line using MSP combined with DNA sequencing." (PMID 24255663, 2013).